BRD4 (bromodomain containing 4)
Diseases named in the same sentence as BRD4 in open-access papers (continued):
Sharing a sentence is not in itself a finding about the gene and the disease.
tumor (535 papers, 2012 to 2026). "Because Krt14-Cre remains active in NC cells, any residual floxed alleles would be deleted during tumor progression, making it highly improbable that a Brd4::Nutm1-positive tumor retains intact Sox2." (PMID 41266112, 2026). "One model employs a Brd4::hNUTM1 knock-in allele activated by the FLEx system and Sox2-CreERT2, resulting in widespread fusion expression and consistent tumor formation in the esophagus, including the gastroesophageal junction." (PMID 41266112, 2026). "SE-associated transcriptional programs have been implicated in aggressive tumor phenotypes, metastasis, and resistance to anticancer therapies, and BRD4 is frequently overexpressed in HNSCC, correlating with poor clinical outcomes." (PMID 41614901, 2026). "The clinical relevance of such observations is supported by the demonstration that the levels of BRD4 in tumor-associated macrophages and PAI-1 in tumors are elevated in CRC patients with chemoresistance and correlate with shorter recurrence-free survival." (PMID 41311847, 2025). "BRD4 also regulates inflammatory responses, and studies have suggested BRD4 plays a role in regulating tumor-associated inflammation and immune responses." (PMID 40762981, 2025). "To understand the mechanism underlying the potent anti-tumor effects of BRD4 inhibitors, we performed RNA-seq analysis of treated tumors." (PMID 40370549, 2025). "Instead, the CR-dysfunctional tumor cells displayed a strong REV-ERBα association with the coactivators such as BRD4 and p300." (PMID 39383000, 2024). "The in vivo pharmacodynamic data provided clear evidence that a single administration of of BD-9136 was remarkably efficient in causing a highly efficent and sustained reduction of BRD4 protein levels, specifically within tumor tissues." (PMID 38389844, 2024). "Prior evidence has implicated a key role for BRD4 inhibition in multiple tumor states, including G3MB47,48,51,64 among many others, where dominant phenotypic outcomes on transcription were related to disruption of MYC transcription." (PMID 38664416, 2024). "In clinical prostate cancer tumor samples, BRD4 protein levels were inversely associated with tumor response after radiation therapy." (PMID 36875159, 2023). "The expression of BRD4 was positively associated with tumor purity, and negatively associated with immune infiltration abundance of macrophage, neutrophil and CD8+ T-cell, respectively." (PMID 36711038, 2023). "The proportion of M1 tumor-associated macrophages (TAMs) increased, and the proportion of M2 TAMs decreased upon BRD4 inhibition." (PMID 37685868, 2023). "Previous work has shown that BRD4 inhibition leads to reduced susceptibility of tumor cells to erastin-induced ferroptosis." (PMID 37993451, 2023). "As these genes are markers of BRD4 inhibition in this disease, we infer that these genes reflect differences in drug uptake in the tumors, a likely cause of variability in tumor growth dynamics in the group of animals treated with BMS-986158." (PMID 37259348, 2023). "Another recently developed CRBN-based PROTAC dBET1 has also shown very potent activity in degrading BRD2, BRD3, and BRD4 proteins in association with a potent anti-tumor activity in various AML cell lines." (PMID 36909156, 2023). "For instance, subcutaneous Brd4 PROTAC administration has been shown to cause >90% Brd4 breakdown in tumor tissue." (PMID 37241755, 2023). "Hyperacetylation of H3K27 in DMG is driven by the activity of acetyl-binding, bromodomain and extraterminal (BET) proteins, particularly bromodomain-containing protein 4 (BRD4) which are implicated in tumor progression and aggressiveness." (PMID 34759345, 2022). "In contrast, the combination of the bioorthogonal NPs (PED + N3@PGDA7) and PDT dramatically regressed 95% of tumour growth, which was 1.5-fold more efficient than BRD4 degradation alone caused by PED + N3@PGDA7 treatment." (PMID 35882867, 2022).
tumor (continued). "BRD4 inhibition was also shown to decrease M2 tumor-associated macrophage (TAM) proliferation, particularly by directly inhibiting HIF1α expression in tumor cells, thereby inhibiting the secretion of M2-promoting colony-stimulating factor 1 (CSF1)." (PMID 36139513, 2022). "To further explore the therapeutic potential of SE-driven transcriptional dependencies in G3-MB, we evaluated the inhibitory effects of targeting SE complex components (BRD4 or CDK7) in combination with targeting SE-associated tumor-dependent effector genes." (PMID 36273157, 2022). "Deficiency in BRD4 arginine methylation significantly suppresses tumor growth and sensitizes cells to BET inhibitors and DNA damaging agents." (PMID 36475791, 2022). "BRD4 mediates transcriptional signaling of cyclin D1 and MSDCs in stomal and inflammatory cells that are associated with tumor progression." (PMID 35401196, 2022). "Loss of BRD4 function, both by genetic means as well as by treatment with a BRD4 inhibitor, leads to sustained inhibition of proliferation of tumour cells, induction of differentiation, and ultimately apoptosis." (PMID 35444289, 2022). "Human SAGA and BRD4, the mammalian homologue of S. pombe Bdf2, have been implicated in the transcriptional regulation of oncoproteins and tumor suppressors." (PMID 35157728, 2022). "BRD4 densely occupies super-enhancers and its inhibition thus reduces c-Myc transcription, causing an anti-tumor effect." (PMID 33888130, 2021). "For instance, a number of recent studies have shown that BRD4 can affect tumor-associated macrophages (TAM) in solid tumors." (PMID 34336890, 2021). "Recently, the pro-tumor activity of c-Myc has been linked to transcriptional and epigenetic regulation by BRD4, a member of the Bromodomain and Extra Terminal (BET) domain-containing family of proteins." (PMID 33006750, 2020). "Our current study strongly supports a collaborative role of the integrin/FAK signaling axis and BRD4-associated epigenetic network in NSCLC tumor cells." (PMID 32793596, 2020). "Here, the authors report a new BET inhibitor, NHWD-870, with improved potency compared to previous BET inhibitors, and show that it suppresses BRD4 and targets tumour associated macrophages." (PMID 32286255, 2020). "Given the susceptibility of the NF-KB-associated pathways to BRD4-dependent epigenetic regulation, we next set out to examine their involvement in tumor cell responses to co-inhibition of integrin/FAK-dependent signaling and BRD4." (PMID 33006750, 2020). "We further assessed the association between BRD4 expression and tumor size from our 87 cases of EACs and found that BRD4 mRNA levels detected by qPCR were significantly associated with tumor size, poor tumor differentiation, and shorter survival." (PMID 32175692, 2020). "Conversely, RNAPolII occupancy at these promoters was comparable in skeletal muscles from (+)-JQ1-treated C26-tumor-bearing mice and control muscles, suggesting that BRD4 blockade prevented RNAPolII association at these promoters." (PMID 29167426, 2017). "Notably, the synergistic effect of TOP1 and BRD4 inhibition is relatively selective for cancer cells, mostly sparing normal cells and highlighting tumor susceptibility to transcriptional defects." (PMID 41155268, 2025). "In addition to downregulating c-MYC and directly inhibiting the proliferation of tumor cells, the BRD4 inhibitor NHWD-870 blocks the proliferation of tumor-associated macrophages (TAMs) through various mechanisms." (PMID 38811964, 2024). "Our recent work demonstrated a tumor microenvironment mechanism by which CAF-associated inflammatory paracrine IL6/IL8-JAK2 signaling induces BRD4 activation by phosphorylation in CRC, leading to chromatin reprogramming through increased enhancer and super-enhancer activity." (PMID 36600243, 2023). "Based on these findings, it was hypothesized that circCUX1 subtypes encoded by p113 subtypes increase tumor growth by transactivating ZRF1/BRD4." (PMID 37091173, 2023).
tumor (continued). "Notably, compared to the BRD4-WT group, the BRD4 mutation group significantly retarded tumor growth and tumor mass." (PMID 37737256, 2023). "Taken together, these data indicated that ectopic expression of BRD4 contributed to the occurrence of tumour and was associated with a poorer prognosis in patients with NB, revealing that BRD4 could be an important therapeutic target in patients with NB." (PMID 35303940, 2022). "Of note, the ASO-mediated inhibition of MYC eRNA expression may be superior compared to an alternative strategy, in which BRD4 inhibitors also suppressed tumor cell-associated MYC expression." (PMID 35039581, 2022). "We observed Brd4, Cul3, and Trip12 to be commonly mutated genes across different tumor types, suggesting that there may be common mechanisms perturbed by the Onc2.3 transposon to drive tumorigenesis in the absence of oncogenic events." (PMID 33435458, 2021). "In addition to possible clonal heterogeneity of the PIK3CA gene mutation, the authors showed that this intra-tumour heterogeneity in glycolysis is further driven by bromodomain-containing protein 4 (BRD4) epigenetic remodelling and cell density." (PMID 34572926, 2021). "In addition, after knockdown of BRD4 or under (+)-JQ1 (an inhibitor of the tumor-driver bromodomain protein BRD4), the expressions of ferroptosis-associated genes GPX4, SLC7A11, and SLC3A2 are downregulated." (PMID 34222241, 2021). "Furthermore, the subcutaneous injection of BRD4 degrader ARV-771 in xenograft tumor mice causes noticeable skin discoloration, which is consistent with the phenotype of Brd4 depleted mice." (PMID 34350175, 2021). "Furthermore, co-expression of BRD4 and PD-L1 was positively correlated with high tumor mutation burden, which contributed to poor OS in AML patients." (PMID 33658927, 2020). "Combined, our chemical inhibitor screening, gene knockdown and bioinformatic analyses consistently indicate a collaborative role of the integrin-FAK pathway and BRD4/Myc-linked epigenetic network in controlling tumor cell variability in NSCLC, regardless state of KRAS or EGFR." (PMID 32793596, 2020). "Furthermore, BRD4 was associated with pre-menopausal status, large tumor size, and high Ki-67 expression, which are characteristics that are generally associated with a basal subtype." (PMID 30029633, 2018). "On the other hand, the favorable clinical outcome associated with BRD4 expression in tumors with high levels of T-bet+ TILs may reinforce the T-bet+ TIL-driven tumor immune surveillance." (PMID 30029633, 2018). "The fact that BRD4 inhibition could induce a small decrease in MDSCs within BRD4 myeloid–deficient mice with slightly smaller tumor volumes suggested the potential for the ability of inhibitors to exert a direct effect on tumor cells." (PMID 40762981, 2025). "Based on their mechanism of action, these techniques to stimulate ferroptosis may be more effective for BRD4-deficient tumour cells because they can partly compensate for the insensitivity of ferroptosis caused by metabolism disorders due to the lack of BRD4 expression." (PMID 36309482, 2022). "Moreover, exogenous IL-33 mimicked the effects observed in case of injury and cooperated with KRAS mutation to activate the neoplasia-specific and BRD4-dependent gene expression program, associated with an accelerated appearance of pancreatic intraepithelial neoplasia." (PMID 34023857, 2021). "However, the association between BRD4 and tumor-related inflammation in RCC remains unknown and the underlying molecular mechanisms have not been studied." (PMID 32303673, 2020). "Besides the impacts on cell survival and tumor growth, inhibition of the integrin-FAK axis and BRD4-linked epigenetic network may alter cytokine pathways and tumor microenvironments." (PMID 32793596, 2020). "In addition, we tested whether BRD4 inhibition rendered tumor cells more susceptible to CD8-mediated lysis, both in vitro and in vivo." (PMID 31653272, 2019).
tumor (continued). "In addition, when the cohort was divided into three groups, there was a significant association between BRD4 expression and OS after controlling for clinicopathological parameters (i.e., tumor grade, stage, metastasis), age, and sex in a multivariable analysis (P = 0.0063)." (PMID 29796168, 2018). "Our finding that BRD4 expression is elevated in a fraction of adjacent non-tumor liver tissue, albeit to a lesser extent than in tumor tissue, raises a potential concern for the future clinical utility of BRD4 inhibitors in human HCC, as improper drug use may cause liver damage." (PMID 26575167, 2016). "Polymorphisms in several other tumor cell autonomous metastasis susceptibility genes identified in our laboratory including Sipa1, Rrp1b, and Brd4 are prognostic only in ER+ patients, and stable expression of Brd4 can also differentially regulate the Tpx2 network." (PMID 22693453, 2012). "Its expression is markedly elevated in GBM relative to normal brain tissue, implicating BRD4 in tumor initiation, progression and therapeutic resistance." (PMID 41828493, 2026). "Collectively, Exo-BSA@dBET6 can exert anti-tumor effects by inhibiting BRD4 protein expression, and modification of dBET6 with exosomes and albumin nanoparticles markedly enhanced its anti-tumor efficacy in vitro." (PMID 41525248, 2026). "Exo-BSA@dBET6 can elevate cellular ROS levels, reduce mitochondrial membrane potential, and enhance the expression of the apoptotic protein caspase-3 by specifically targeting the BRD4 protein, ultimately inducing tumor cell apoptosis." (PMID 41525248, 2026). "Previous studies have demonstrated the high sensitivity of PEL cells to BET inhibitors, and BRD4 silencing effectively blocks tumor cell proliferation." (PMID 42224297, 2026). "There has been substantial investigation into the use of BRD4 inhibitors to directly target tumor cells, and several BRD4 inhibitors are being tested in clinical trials." (PMID 40762981, 2025). "Inhibition of epigenetic regulators like BRD4 suppresses hedgehog pathway genes and curbs tumor growth, especially in cases resistant to Smoothened antagonists." (PMID 40565099, 2025). "We used linear regression to model the effects of copy number, BRD4 focal deletion status, and tumor type on BRD4 expression." (PMID 40112818, 2025). "JQ1 decreased PD-L1 expression through BRD4-dependent occupancy of the CD274 promoter, thereby increasing tumor-associated CD8+ T cells producing IFN-γ and granzyme B in lymphoma, prostate, and oral squamous cell carcinoma models." (PMID 41583469, 2025). "The X-ray-responsive PROTAC nanomicelle represented a novel approach for achieving precise, X-ray-triggered protein degradation and enhancing tumor sensitivity to radiotherapy through BRD4 proteolysis." (PMID 40284496, 2025). "DNA-methylation-based analysis classified the sample as a CNS embryonal tumor with BRD4-LEUTX fusion “novel entity” (prediction score = 0.99)." (PMID 41353556, 2025). "Based on our recent observations on the intrinsic link between FAK and the BRD4‐MYC axis in solid tumors, we next explored the feasibility of the FAK and BRD4 inhibitors—based co‐inhibition for MYChigh CRC tumor cell lines." (PMID 40959971, 2025). "One intriguing finding of this study is that BRD4 inhibitor AZD5153 displayed much higher potency than JQ1 in inhibition of NEPC tumor growth." (PMID 40370549, 2025). "Upon exposure to X-ray radiation, the diselenide bonds in RCNprotac are broken, leading to the specific release of MZ1 for tumor BRD4 protein degradation." (PMID 41012497, 2025). "These annotations indicate that HPV+ tumor super-enhancers coordinate a G2/M checkpoint and chromosomal segregation program that is selectively repressed by BRD4 inhibition." (PMID 41323280, 2025). "We showed that JQ1, a potent inhibitor of BRD4, dose-dependently reduced tumor cells viability in PDSES." (PMID 39774014, 2025).
tumor (continued). "In ovarian cancer, targeting CCR2+ TAMs with BRD4 specific inhibitor (ABBV-075) selectively depletes this pro-tumor subset, overcoming adaptive resistance to anti-VEGF therapy while sparing M1-like macrophages." (PMID 41583469, 2025). "The present study provides evidence for an additional immunomodulatory role of BRD4 inhibitors, including direct pro-apoptotic effects on MDSCs and reduced tumor-soluble factors responsible for MDSC expansion and recruitment to the TME." (PMID 40762981, 2025). "The in vivo experiments demonstrated that NANOVB markedly inhibited tumor growth, extended the survival in mice, and reduced the expression of BRD4 and Ki-67 proteins." (PMID 40284496, 2025). "The polymeric nanoparticle exhibited prolonged blood circulation and enhanced tumor penetration, effectively increasing BRD4 degradation and reducing the tumor burden in both xenograft and syngeneic mouse models." (PMID 40284496, 2025). "BRD4 promotes pro-tumor M2-like polarization by driving MAF transcription, whereas BRD2 contributes predominantly to pro-inflammatory gene expression." (PMID 41583469, 2025). "Beyond single-target combinations, dual HDAC3/BRD4 inhibitors simultaneously disrupt oncogenic transcription and chromatin regulation, broadly enhancing apoptosis across multiple tumor models." (PMID 41583469, 2025). "The inhibitory effect on BRD4 in tumor cell super-enhancers was predominantly observed after 6 hours of exposure to 500 nM of JQ1 in GC cells." (PMID 40966274, 2025). "Upon tumor establishment in hatched zebrafish embryos, treatment with 7.5 μM BRD4 inhibitor JQ1 was administered." (PMID 40308947, 2025). "Previous studies showed that the long and short isoforms of BRD4 act differently in tumor progression and metastasis." (PMID 40869394, 2025). "We next asked to what extent BRD4 focal deletions alter BRD4 expression relative to the copy number of the larger amplicon and to the tumor type of origin." (PMID 40112818, 2025). "It is also possible that inhibition of a tumor–MDSC interaction was interrupted after BRD4 inhibition, as additional tumor-secreted soluble factors, including chemokines (CCL2, CXCL3, and CXCL5), were all reduced after BRD4 inhibition in vitro." (PMID 40762981, 2025). "CircNR3C1 interacts with BRD4, disrupting the BRD4/C-myc complex that promotes BC progression, and in vivo studies showed that ectopic expression of C-myc can partially reverse the tumor-suppressive effects of circNR3C1." (PMID 40223811, 2025). "This modular chemical scaffolding enables the controlled, tumor‐triggered degradation of BRD4 and CDK9, with potential therapeutic implications, including the possible use in combination treatments." (PMID 41362117, 2025). "BRD4 is most enriched in super-enhancers that promote the expression of tumor growth and development-enhancing factors, including c-MYC." (PMID 40650308, 2025). "In the present study, enhancement of anti–PD-L1 therapy after BRD4 inhibition was seen in multiple tumor models, along with a significant reduction of both intratumoral and splenic MDSCs." (PMID 40762981, 2025). "ARV-825, composed of OTX015 and the CRBN E3 ligase ligand, achieves a DC50 value of 4.75 nM against BRD4 and effectively suppresses tumor growth." (PMID 40507351, 2025). "JQ1, a small-molecule BRD4 inhibitor, has demonstrated efficacy across various tumor types and synergizes with other targeted therapies." (PMID 40843352, 2025). "The nanocages demonstrated effective BRD4 degradation and successfully suppressed tumor growth with 58.7% tumor growth inhibition in vivo." (PMID 41049269, 2025). "BRD4 inhibition reduced the release of tumor-derived cytokines and chemokines, raising the possibility of an indirect effect on MDSCs via decreased generation of MDSCs and/or reduced intratumoral infiltration." (PMID 40762981, 2025).